RN7SL802P (RNA, 7SL, cytoplasmic 802, pseudogene)
Gene: Miscellaneous RNA gene on chromosome 5 (101,581,830 to 101,582,128, forward strand). Ensembl gene ENSG00000277506.
Homologues: Orthologues: chimpanzee Metazoa_SRP (97% identical), macaque Metazoa_SRP (91% identical). Paralogues in human: RN7SL1 (80% identical), RN7SL2 (79% identical), RN7SL3 (78% identical), RN7SL655P (78% identical), RN7SL664P (78% identical), RN7SL448P (77% identical), RN7SL296P (77% identical), RN7SL711P (77% identical), RN7SL714P (77% identical), RN7SL344P (76% identical), RN7SL45P (76% identical), RN7SL408P (76% identical), and 701 more.